SLC39A8 (solute carrier family 39 member 8)
Diseases named in the same sentence as SLC39A8 in open-access papers (continued):
Sharing a sentence is not in itself a finding about the gene and the disease.
Sepsis (11 papers, 2011 to 2025). Sepsis is defined as life-threatening organ dysfunction caused by a dysregulated host response to infection. "Glycosylation of zrt-/irt-like protein 8(ZIP8), encoded by SLC39A8, is significantly increased in monocytes from patients with sepsis." (PMID 40959280, 2025). "For instance, solute carrier family 39 member 8 (SLC39A8)-driven ferroptosis is a primary contributor to monocyte loss in sepsis patients, resulting in immunosuppression, while inhibiting SLC39A8 can reduce LPS-induced lipid peroxidation." (PMID 38844964, 2024). "Importantly, elevated SLC39A8 mRNA expression in monocytes has also been associated with sepsis severity, and more recently SLC39A8 was identified as a gene affecting the course of malaria infection in West African children." (PMID 23738776, 2013). "Elevated SLC39A8 expression enhances lipid peroxidation while downregulating GPX4, FTH1, indicating that SLC39A8-driven ferroptosis plays a crucial role in the depletion of monocytes during sepsis." (PMID 40959429, 2025). "Ferroptosis mediated by solute carrier family 39 member 8 (SLC39A8) plays a significant role in the depletion of monocytes among individuals with sepsis, thereby leading to immune system suppression." (PMID 39267971, 2024). "Moreover, Slc39a8(neo/neo) fetal fibroblasts exhibited decreased Zn uptake and increased NFκB activation; consistent with this finding, mice fed a Zn-deficient diet showed disproportionate inflammation caused by polymicrobial sepsis—concomitant with loss of normal IKK regulation." (PMID 31521203, 2019). "In addition, another study reported that the expression of SLC39A8 (a zinc importer) and the intracellular shift of zinc increased during sepsis, resulting in decreased serum zinc concentrations." (PMID 39275159, 2024). "In the acute hyperinflammatory phase, distinct subsets of monocyte-like cells (CD163+SLC39A8+CALR+ infMonos) and Tinf cells (MX1+IRF1+ISG15+) emerged, a phenomenon also observed in patients with sepsis and COVID-19." (PMID 40251340, 2025). "Zinc transporter ZIP8 (SLC39A8) is a transcriptional target of NF-κB, described as the most significantly up-regulated transporter in response to cytokines, bacteria, and sepsis." (PMID 28083748, 2017).
congenital disorder of glycosylation (10 papers, 2019 to 2026). Congenital disorder of glycosylation (CDG) is a fast growing group of inborn errors of metabolism characterized by defective activity of enzymes that participate in glycosylation (modification of proteins and other macromolecules by adding and processing of oligosaccharide side chains). "In addition, to determine the function of SLC39A8 mutants associated with congenital disorder of glycosylation (CDG) and Leigh syndrome, cell transfection studies were performed." (PMID 35832795, 2022). "Since Mn is a cofactor for beta-1,4-galactosyltransferase, SLC39A8 variants are associated with a congenital disorder of glycosylation (CDG), characterized by deficient galactosylation of glycan chains of glycoproteins." (PMID 34246313, 2021). "Homozygous loss-of-function mutations in SLC39A8 result in undetectable serum manganese (Mn) and a Congenital Disorder of Glycosylation (CDG) due to the exquisite sensitivity of glycosyltransferases to Mn concentration." (PMID 32753748, 2020). "SLC39A8-congenital disorder of glycosylation (SLC39A8-CDG) is a rare autosomal recessive metabolic disease of manganese transport, leading to defective glycosylation and mitochondrial dysfunction." (PMID 41669571, 2026). "SLC39A8, a gene located on chromosome 4q24, encodes for the manganese (Mn) transporter ZIP8 and its detrimental variants cause a type 2 congenital disorder of glycosylation (CDG)." (PMID 34246313, 2021).
osteoarthritis (9 papers, 2013 to 2024). A noninflammatory degenerative joint disease occurring chiefly in older persons, characterized by degeneration of the articular cartilage, hypertrophy of bone at the margins and changes in the synovial membrane. "Whereas ZIP8 over-expression in mouse cartilage tissue causes osteoarthritis—another form of inflammatory disease—osteoarthritis is suppressed in chondrocyte-specific conditional Slc39a8(−/−) knockout mice, with concomitant decreases in Zn2+ influx and matrix-degrading enzymes in chondrocytes." (PMID 27166256, 2016). "The product of the SLC39A8 gene was shown to participate in osteoarthritis cartilage destruction." (PMID 32587327, 2020).
lung fibrosis (8 papers, 2022 to 2025). "In IPF lungs and the lungs of aged mice, downregulation of zinc transporter ZIP8/SLC39A8 is associated with alveolar epithelial cell senescence and exacerbation of pulmonary fibrosis." (PMID 40241794, 2025). "Slc39a8 deletion mice exhibit a deficiency in the specific zinc transporter SLC39A8 within AEC2, resulting in spontaneous lung fibrosis." (PMID 38007420, 2023). "To illustrate the role of ZIP8 in AEC2 renewal and lung fibrosis in vivo, we generated a mouse line with targeted deletion of Slc39a8 in the adult AEC2 compartment — SFTPC-CreER Rosa26-tdTomato Zip8fl/fl (Zip8AEC2) — by crossbreeding Slc39a8-floxed mice with SFTPC-CreER Rosa26-tdTomato mice." (PMID 35389887, 2022).
Zinc deficiency (8 papers, 2012 to 2025). A deficiency of the essential metal Zinc; an essential cofactor for many enzymes. "This is one difference between SLC39A8 and, say, SLC39A4—mutations in which are well-known to cause acrodermatitis enteropathica, zinc-deficiency (AEZ) type." (PMID 31521203, 2019).
Leigh syndrome (7 papers, 2018 to 2025). "Rare mutations in SLC39A8 cause severe congenital disorders of glycosylation (CDG type IIn) or mitochondrial dysfunction (Leigh syndrome)." (PMID 41178719, 2025). "We document two novel variants associated with Leigh syndrome-like disease presentation of SLC39A8-CDG." (PMID 34246313, 2021). "We document two novel variants associated with Leigh syndrome-like disease presentation of SLC39A8-CDG and we show, for the first time, a severe neurological phenotype in association with the already known homozygous A391T missense variant." (PMID 34246313, 2021). "Specific recessive variants in SLC39A8 induce reduced Mn2+ levels in mitochondria, which produces profound developmental delay, dystonia, failure to thrive, and Leigh syndrome." (PMID 33426505, 2020). "Mutations in the SLC39A8 gene are associated with congenital disorder of glycosylation type II and Leigh syndrome." (PMID 29453449, 2018). "The approach was guided by insights from human genetics demonstrating that loss of function variants of SLC39A8 linked to CDG and Leigh syndrome and common variants linked to autoimmune, neurologic, and metabolic diseases reduces systemic Mn levels." (PMID 41178719, 2025). "So, judging from our cases and those already documented in literature, cerebral atrophy, cerebellar atrophy and a Leigh syndrome-like pattern are common features in SLC39A8-CDG and they can be present alone or in different combinations." (PMID 34246313, 2021). "Whereas consensus SLC39A8 increased 54Mn uptake in wild-type cells, all four selected alleles lacked ZIP8-mediated Mn uptake into the cells—thereby providing an explanation for the severe Mn deficiency seen in those CDG and Leigh syndrome patients." (PMID 31521203, 2019). "In particular, SLC39A8-CDG may present with the clinical, biochemical and neuroradiological features of Leigh syndrome-like mitochondrial disease, probably due to reduced activity of Mn-dependent superoxide dismutase (SOD), a reactive species scavenger in mitochondria." (PMID 34246313, 2021).
neuroblastoma (7 papers, 2019 to 2025). Neuroblastoma (NB) is the most common solid, extracranial childhood tumor. "These luciferase constructs and SLC39A8 or scramble siRNA were transfected into human neuroblastoma SH-SY5Y cells, and the treatment with forskolin, a cAMP analog, stimulated cAMP signaling." (PMID 39435657, 2024). "ZIP8 (SLC39A8) was shown to be involved in the progression of neuroblastoma, metastasis, and sensitivity to chemotherapy." (PMID 37107291, 2023).
Cerebellar atrophy (6 papers, 2018 to 2025). Cerebellar atrophy is defined as a cerebellum with initially normal structures, in a posterior fossa with normal size, which displays enlarged fissures (interfolial spaces) in comparison to the foliae secondary to loss of tissue. "Two case series from 2015 identified individuals with severe mutations in SLC39A8 presenting with a constellation of severe symptoms including intellectual disability, developmental delay, cerebellar atrophy, growth abnormalities, and seizures." (PMID 32753748, 2020). "Inactivating mutations in the metal transporter gene SLC39A8, which codes for the transporter protein ZIP8, result in intellectual disability, cranial malformations, cerebellar atrophy, hypotonia, low blood manganese, and impaired glycosylation." (PMID 33790950, 2021).
inflammatory bowel disease (6 papers, 2017 to 2025). A spectrum of small and large bowel inflammatory diseases of unknown etiology. "Transcriptomic analysis revealed that alkaline ceramidase 1 (ACER1), an enzyme that regulates the levels of ceramides, is a promising therapeutic target for inflammatory bowel diseases associated with SLC39A8." (PMID 40933952, 2025). "The metal ion transporter SLC39A8 is associated with physiological traits and diseases, including blood manganese (Mn) levels and inflammatory bowel diseases (IBD)." (PMID 38839750, 2024). "The metal transporter SLC39A8 is linked to blood manganese (Mn) levels and inflammatory bowel diseases (IBD)." (PMID 38839750, 2024).
Intellectual disability (6 papers, 2018 to 2025). "Mutations in the conserved sequences of SLC39A8 cause substantial reduction in Mn concentrations and severe phenotypes with intellectual disability and developmental delay, cranial asymmetry, and dwarfism." (PMID 30619481, 2018). "The two associations with an MOI that was unsupported in the literature were between UCHL1 and dominant ‘Inherited optic neuropathies’ and between SLC39A8 and dominant ‘Intellectual disability’." (PMID 36928819, 2023).
lung carcinoma (6 papers, 2020 to 2025). "Lastly, SLC39A8 (Solute Carrier Family 39 Member 8), a zinc transporter, is dysregulated in lung cancer and may influence tumor behavior by breaking homeostasis." (PMID 40565055, 2025).
Obesity (6 papers, 2013 to 2025). Accumulation of substantial excess body fat. "Genetic variants in SLC39A8 have previously been associated to several cardiovascular risk factors such as HDL-cholesterol, blood pressure, obesity, and activation of plasminogen." (PMID 23372645, 2013). "Among the top 20 ABF signals, half are within/near genes known to have prior genome‐wide significant associations with obesity, BMI, and/or weight, while the P‐value approach assigns rank 29 to one of these signals (rs13107325 in SLC39A8/ZIP8, a zinc transporter)." (PMID 26411566, 2015).
Parkinson disease (6 papers, 2019 to 2026). A progressive degenerative disorder of the central nervous system characterized by loss of dopamine producing neurons in the substantia nigra and the presence of Lewy bodies in the substantia nigra and locus coeruleus. "Conversely, genetic variants of SLC39A8 have been linked to hypomanganesemia and a host of physiological perturbations ranging from severe developmental disorders to Parkinson’s disease, IBD, and cardiovascular disease." (PMID 41178719, 2025).
prostate carcinoma (6 papers, 2016 to 2025). A carcinoma that arises from epithelial cells of the prostate gland. "SLC30A1 expression was increased and SLC39A8 decreased in MAC-MT cells in cancer compared to non-tumor samples, the overall effect of which may be to increase zinc efflux, potentially counteracting the known decreased zinc concentration associated with prostate cancer." (PMID 34936871, 2021).
colorectal cancer (5 papers, 2013 to 2024). A primary or metastatic malignant neoplasm that affects the colon or rectum. "RNA sequencing data showed that SLC30A10 expression in colorectal cancer negatively correlates with its functional antagonists SLC39A14 and SLC39A8." (PMID 39596116, 2024). "Using two model human cancer cell lines (HCT-15 for colorectal cancer and HuTu80 for duodenal carcinoma) we generated HCT-15 and HuTu80 knockout cell lines for the SLC39A14 gene and an HuTu80 knockout cell line for the SLC39A8 gene." (PMID 39596116, 2024). "There was a significant difference in the expression distribution of TFAP2C, SLC39A8, and AKR1C1 genes between the cetuximab responders and non-responders in colorectal cancer (P < 0.05)." (PMID 34249766, 2021).
anemia (4 papers, 2012 to 2024). A reduction in the number of red blood cells, the amount of hemoglobin, and/or the volume of packed red blood cells. "Thus, it can be concluded that the observed phenotype of stunted growth, dysregulation of hematopoiesis, anemia, multiple-organ failures in development, and in utero and neonatal lethality is indeed due to lowered ZIP8 caused by the Slc39a8(neo/neo) genotype." (PMID 22563477, 2012). "Finally, we wished to confirm that the observed phenotype (anemia and newborn lethality) was indeed due to the neo-cassette-mediated down-regulation of Slc39a8 gene expression during mouse embryo development." (PMID 22563477, 2012). "Slc39a8(neo/neo) knockdown mice exhibit 10–15% of wild-type ZIP8 mRNA and protein levels, and show pleiotropic phenotype of stunted growth, neonatal lethality, multi-organ dysmorphogenesis, and dysregulated hematopoiesis manifested as severe anemia." (PMID 30013175, 2018).
asthma (4 papers, 2020 to 2025). "Further analysis suggests that variants in POC5 and SLC39A8 may contribute to the observed associations between BMI and body fat percentage, and asthma and COPD." (PMID 40869120, 2025). "The identification of missense variants, rs13107325 and rs2307111 in SLC39A8 and POC5, respectively, suggests that these genes may have some associations or roles in the development of CRDs, including asthma and COPD." (PMID 40869120, 2025). "The discovery of the missense variants rs13107325 and rs2307111 in SLC39A8 and POC5, respectively, in addition to other intronic and synonymous SNPs suggests that these SNPs may have some roles in the development or progression of asthma and COPD." (PMID 40869120, 2025). "To date, however, few studies have reported on the relationship between SLC40A1, SLC39A8, CA2, and asthma, or examined the functional roles of the five IMR genes in iron homeostasis imbalance." (PMID 37123407, 2023). "Among the top flow central nodes, several genes, such as SLC39A8, SOX17, and MFAP4 show a direct relationship with asthma and COPD." (PMID 32041952, 2020). "More specifically, it has been found in literature that the expression levels of SLC39A8, SOX17, and MFAP4 might directly affect both asthma and COPD." (PMID 32041952, 2020).
congenital disorder of glycosylation type IIn (4 papers, 2019 to 2022). "Another is a congenital disorder of glycosylation type IIn (SLC39A8-CDG, MIM 616721), caused by SLC39A8 gene mutations." (PMID 36733764, 2022). "Mutations in SLC39A8 are also associated with congenital disorder of glycosylation, type IIn, in which patients display normal localization of the mutant ZIP8 protein, but exhibit low blood Zn and Mn levels as well as high levels of these cations in urine, suggesting renal wasting of the cations." (PMID 35745255, 2022).
Hypertension (4 papers, 2021 to 2025). The presence of chronic increased pressure in the systemic arterial system. "Genes C2orf16, ZNF512 and COBLL1 were also previously reported, as was SLC39A8 in chromosome (CHR) 4, which plays a role in hypertension and has been found to be associated to type-2 diabetes." (PMID 34145383, 2021).
alcoholism (3 papers, 2019 to 2024). "Our drug-gene interaction search also revealed a link between the OA-risk gene SLC39A8 (POA = 2.14 × 10–7, PMD = 0.080) and risk of developing alcoholism." (PMID 34603368, 2021).
bladder cancer (3 papers, 2012 to 2025). "For example, a pan-cancer TCGA analysis found that tumor overexpression of SLC39A3, SLC39A5, and SLC39A11 was associated with better overall survival after bladder cancer diagnosis, whereas tumor overexpression of SLC39A2, SLC39A8, SLC39A9, and SLC39A14 was associated with poorer survival." (PMID 39789109, 2025).
cervical cancer (3 papers, 2021 to 2025). A primary or metastatic malignant neoplasm involving the cervix. "Previously, we established a ZIP8-knockout (KO) cell model by knocking out the SLC39A8 gene in the HeLa human cervical cancer cell line using the CRISPR/Cas9 system." (PMID 40559995, 2025).
Cirrhosis (3 papers, 2020 to 2025). A chronic disorder of the liver in which liver tissue becomes scarred and is partially replaced by regenerative nodules and fibrotic tissue resulting in loss of liver function. "SLC30A10 and SLC39A8 encode metal ion transporters and PNPLA3 and TM6SF2 are known genes associated with fatty liver and cirrhosis." (PMID 32247823, 2020). "Conceivably, ZIP8, a manganese transporter encoded by the SLC39A8 gene that influences N-glycan branching, could be involved in lower circulating levels of GlycA in patients with cirrhosis." (PMID 39859175, 2025). "Evidently, further study is needed to delineate more precisely the mechanisms responsible for the lower GlycA levels in cirrhosis and the role of ZIP8/SLC39A8 therein." (PMID 39859175, 2025).
colitis (3 papers, 2020 to 2024). Inflammation of the colon. "Two studies have since reported that A393T mice recapitulating the A391T human variant in SLC39A8 exhibit increased intestinal inflammation in the dextran sulfate sodium (DSS) model of colitis." (PMID 39322808, 2024). "In summary, we found that the SLC39A8 variant affects colonic mucosal–luminal trace metal homeostasis, changes the microbiome prior to disease onset, and promotes eventual spontaneous colitis representing a model for how it could promote disease in humans." (PMID 39322808, 2024). "Moreover, Slc39a8 deficiency in IECs exacerbates colitis after intestinal epithelial injury." (PMID 38839750, 2024). "Taken together, the data from both the acute DSS colitis and TNBS colitis model, as well as the chronic DSS colitis model, indicated that the loss of epithelial Slc39a8 exacerbates mucosal barrier damage and promotes colon inflammation and colitis." (PMID 38839750, 2024). "The Slc39a8-IEC KO mice developed clinical symptoms of colitis with increasing severity starting on day 2 of the second cycle and peaking on day 11, whereas the symptoms in control mice were delayed and significantly reduced in severity." (PMID 38839750, 2024). "Thus, our study provides insights into how Slc39a8 contributes to Mn absorption and protect animals from colitis." (PMID 38839750, 2024). "In addition to the findings for Slc39a8-IEC KO intestines, our data demonstrate that dietary Mn deficiency upregulates Acer1 expression in the intestine and that treatment with an Acer1 inhibitor mitigates colitis in Mn-deficient mice." (PMID 38839750, 2024). "We treated Slc39a8-IEC KO and control mice with 3% DSS in the drinking water to induce colitis (inflammatory phase) and then placed on regular drinking water (recovery phase)." (PMID 38839750, 2024).
fatty liver (3 papers, 2020 to 2025). "Of further relevance, the SLC39A8 locus may also confer protection against the progression of hepatic steatosis to steatohepatitis and fibrosis." (PMID 39859175, 2025).